TIFAB (TIFA inhibitor)
Description:
Inhibits TIFA-mediated TRAF6 activation possibly by inducing a conformational change in TIFA.
Tractability: No criterion of Open Targets' tractability assessment is met for any kind of drug.
Gene: Protein-coding gene on chromosome 5 (135,444,226 to 135,452,351, reverse strand). Ensembl gene ENSG00000255833.
Gene Ontology:
Molecular function: deubiquitinase activator activity; protein binding; ubiquitin-specific protease binding; ribonucleoprotein complex binding
Biological process: auditory behavior; cochlea development; cochlea morphogenesis; craniofacial suture morphogenesis; genitalia development; genitalia morphogenesis; hard palate morphogenesis; inner ear development; inner ear morphogenesis; learned vocalization behavior; mastication; negative regulation of canonical NF-kappaB signal transduction; negative regulation of relaxation of muscle; negative regulation of saliva secretion; neuromuscular process controlling balance; peristalsis; regulation of canonical NF-kappaB signal transduction; regulation of muscle organ development; thorax and anterior abdomen determination; toll-like receptor signaling pathway; trigeminal nerve development; vestibulocochlear nerve formation; cellular response to cAMP; cellular response to Thyroid stimulating hormone; positive regulation of canonical NF-kappaB signal transduction; and 2 more
Cellular component: cytoplasm; cytosolic large ribosomal subunit
Genetic constraint (gnomAD): Loss-of-function variants: 0 observed, 0.26 expected, observed/expected ratio (o/e) 0, 90% interval 0 to 1.87. That is too few expected variants to judge how well the gene tolerates losing a copy. Missense variants: 222 observed, 209.38 expected, observed/expected ratio (o/e) 1.06, 90% interval 0.95 to 1.18. Synonymous variants: 116 observed, 98.68 expected, observed/expected ratio (o/e) 1.18, 90% interval 1.01 to 1.37.
Homologues: Orthologues: chimpanzee TIFAB (98% identical), macaque TIFAB (92% identical), dog TIFAB (78% identical), pig TIFAB (78% identical), mouse Tifab (73% identical), rat Tifab (73% identical). Paralogues in human: TIFA (27% identical).
Diseases named in the same sentence as TIFAB in open-access papers:
TIFAB is named in the same sentence as 10 diseases in open-access papers, as found by Europe PMC text mining. Sharing a sentence is not in itself a finding about the gene and the disease. The quoted sentences say what the papers report.
leukemia (2 papers, 2021 to 2022). A malignant (clonal) hematologic disorder, involving hematopoietic stem cells and characterized by the presence of primitive or atypical myeloid or lymphoid cells in the bone marrow and the blood.
aneurysm (1 paper, 2021). Bulging or ballooning in an area of an artery secondary to arterial wall weakening. "Furthermore, our Pearson correlation analysis showed that some of genes (namely, ST6GALNAC1, TIFAB, and CCDC85B) may be informative in assessing IA risk, as their intraluminal expression was related to aneurysm size, IA wall enhancement, or both." (PMID 34441376, 2021). "TIFAB, which encodes a regulator of TRAF proteins that transduce extracellular inflammatory signals that mediate the NF-kB pathway, was also positively correlated with aneurysm size (and with IA wall enhancement, albeit not significantly)." (PMID 34441376, 2021).
bone marrow failure (1 paper, 2016). "TIFAB forms a complex with TRAF6, reducing its stability by a lysosome-dependent mechanism, and mice transplanted with Tifab−/− HSPCs display a bone marrow failure like disease with cytopenias and myeloid differentiation skewing." (PMID 27733853, 2016).
Coronary Artery Aneurysm (1 paper, 2023). "Similarly, TIFAB, a gene shown to be a susceptibility locus in patients with Kawasaki Disease for Coronary Artery Aneurysm, was another gene that was highly upregulated in RHD." (PMID 37018379, 2023).
myeloid malignancies (1 paper, 2023). "Furthermore, Niederkorn and collaborators found that TIFAB (fork-associated B domain), a protein commonly involved in myeloid malignancies, regulates USP15 signaling to substrates in hematopoietic cells." (PMID 37373211, 2023).
hematological diseases (1 paper, 2023). "It is important to emphasize that the TIFAB gene is located on chromosome five in the 5q31.1 region and is commonly deleted in hematological diseases, including MDS." (PMID 37373211, 2023).
TIFAB also shares sentences with these, for which no sentence is quoted: carcinoma (1 paper); glioma (1); Kawasaki disease (1); uterine sarcoma (1).